PANDAR (promoter of CDKN1A antisense DNA damage activated RNA)
Diseases named in the same sentence as PANDAR in open-access papers (continued):
Sharing a sentence is not in itself a finding about the gene and the disease.
thyroid cancer (5 papers, 2017 to 2025). "Overexpression of miR-637 suppresses thyroid cancer progression, an effect that can be reversed by PANDAR overexpression." (PMID 40713854, 2025). "It has recently been reported that PANDAR is highly expressed in thyroid gland carcinoma and can promote tumour proliferation and inhibit apoptosis." (PMID 34476001, 2021). "In this study, we explored the expression of PANDAR in thyroid gland carcinoma tissues and thyroid gland carcinoma cell lines." (PMID 34476001, 2021). "In this study, we found that PANDAR is highly expressed in thyroid gland carcinoma tissues and cell lines." (PMID 34476001, 2021). "The data showed that knocking down PANDAR expression significantly inhibited thyroid gland carcinoma cell proliferation and colony formation, suggesting that PANDAR can promote thyroid gland carcinoma cell proliferation." (PMID 34476001, 2021). "The results showed that the relative expression of PANDAR mRNA was significantly higher in thyroid carcinoma tissues than in adjacent normal tissues (P < 0.001)." (PMID 34476001, 2021). "In this study, we explored the expression pattern of PANDAR in thyroid cancer tissues and thyroid cancer cell lines." (PMID 28507479, 2017). "Having found the effect of PANDAR downregulation on the proliferation of thyroid cancer cell lines, we then examined the impact of decreased expression of PANDAR on cell cycle in thyroid cancer cells." (PMID 28507479, 2017). "Here, we used the quantitative real-time PCR (qRT-PCR) to determine the expression of PANDAR in 64 thyroid cancer tissues." (PMID 28507479, 2017). "In the present study, we found that PANDAR was highly expressed in thyroid cancer tissues and cell lines." (PMID 28507479, 2017). "In addition, the mechanism of action of PANDAR in the regulation of the proliferation and metastasis of thyroid gland carcinoma cells by miR-637 was examined in vitro and vivo." (PMID 34476001, 2021). "In this study, we clarified the anti-thyroid gland carcinoma mechanism of PANDAR." (PMID 34476001, 2021). "PANDAR negatively correlated with miR-637, and miR-637 overexpression suppressed thyroid gland carcinoma progression, which could be reversed by PANDAR." (PMID 34476001, 2021). "Additionally, we identified miR-637 as a target of PANDAR in thyroid gland carcinoma, and PANDAR can be used as a novel therapeutic target for the treatment of thyroid gland carcinoma." (PMID 34476001, 2021). "Interestingly, the relative expression of PANDAR in the seven thyroid gland carcinoma cell lines (Nthy-ori3-1, K1, TPC-1, K1, FTC133, XTC-1, B-CPAP) was significantly higher than that of the normal cell line Nthy-ori3-1 (P < 0.01)." (PMID 34476001, 2021). "Moreover, we examined Bcl-2 and Bax expression in thyroid cancer cells in response to PANDAR knockdown." (PMID 28507479, 2017). "Taken together, these results illuminated that PANDAR may function as an oncogene involved in the stimulation of thyroid cancer cell proliferation." (PMID 28507479, 2017). "Functional assays in vitro demonstrated that knockdown of PANDAR could inhibit proliferation, cell cycle progression, induces the apoptosis, inhibit invasion of thyroid cancer cells." (PMID 28507479, 2017). "However, few studies have reported the potential role of lincRNA PANDAR in thyroid gland carcinoma." (PMID 34476001, 2021). "PANDAR could promote thyroid gland carcinoma cell proliferation and metastasis." (PMID 34476001, 2021). "Thus, our study provides evidence that PANDAR may function as a potential target for treatment for patients with thyroid cancer." (PMID 28507479, 2017). "Therefore, we speculated that PANDAR overexpression may be correlated with thyroid cancer pathogenesis." (PMID 28507479, 2017). "However, the expression and detailed function of PANDAR in thyroid cancer remains largely unknown and needs to be investigated." (PMID 28507479, 2017). "Overall, PANDAR can suppress miR-637 and induce KLK4 to regulate invasion and migration in thyroid gland carcinoma." (PMID 34476001, 2021).
thyroid cancer (continued). "In thyroid carcinoma, some lncRNA are discussed in the gene regulation of disease progression, such as PTCSC3, with XLOC 051122 and XLOC 006074 in local metastasis and PANDAR as a possible target in pro-apoptotic therapies for carcinoma." (PMID 35594253, 2022). "We found that expression of PANDAR was up-regulated in thyroid cancer tissues compared with adjacent non-tumor tissues." (PMID 28507479, 2017). "To investigate how PANDAR regulates proliferation and metastasis in thyroid gland carcinoma, we transfected the PANDAR plasmid into TPC-1 cells for 72 hours and performed transcriptome sequencing analysis of the differentially expressed downstream non-coding RNAs of PANDAR." (PMID 34476001, 2021).
lung carcinoma (4 papers, 2016 to 2021). "Therefore, we deduced lncRNA PANDAR should be associated with BECN1, and PANDAR involved in the development of lung cancer by regulating autophagy pathway in lung cancer." (PMID 32626525, 2020). "In conclusion, this study has confirmed that lncRNA PANDAR can affect the development of lung cancer by regulating the expression of BECN1 gene." (PMID 32626525, 2020). "The expression of BRANCR, SPRY4-IT1, AB209630, HMlinc717, TUG1, GAS6-AS1 and PANDAR was down-regulated, while the expression of other lncRNAs was up-regulated in lung cancer patients." (PMID 29137343, 2017). "These suggested that increased expression of lncRNA PANDAR could significantly inhibit the growth and proliferation of lung cancer cells and lncRNA PANDAR maybe inhibit the progression of lung cancer through autophagy pathway." (PMID 32626525, 2020). "Beclin1 and Bcl-2 family proteins both have BH3 receptor domain, so we speculated that lncRNA PANDAR would promote the apoptosis of lung cancer cells in mitochondria pathway by increasing Beclin1 expression levels." (PMID 32626525, 2020). "Importantly, a positive association was observed between PANDAR and BECN1 in lung cancer tissues (r = 0.789, P < 0.001)." (PMID 32626525, 2020). "In addition, the autophagy marker LC3-II protein expression levels were also increased when PANDAR expression up-regulated, and this further validated the results of co-transfection experiments indicating that lncRNA PANDAR could increase autophagy levels in lung cancer cells." (PMID 32626525, 2020). "PANDAR by upregulation of BECN1 expression via activating autophagy and apoptosis pathways could inhibit the development of lung cancer." (PMID 34367998, 2021). "So, we concluded that lncRNA PANDAR regulated the development of lung cancer involved in not only autophagy pathway but also apoptosis pathway." (PMID 32626525, 2020). "In lung cancers, significantly dysregulated lncRNAs have been reported, and many of them, e.g., PANDAR, DLX6-AS1, BCYRN1, HNF1A-AS1, ANRIL, MEG3, and others, are involved in lung cancer pathogenesis, cell proliferation, invasion and metastasis, and drug resistance." (PMID 27322209, 2016).
lymph node metastasis (4 papers, 2017 to 2025). "Previously, PANDAR expression was shown to be positively associated with lymph node metastasis and advanced clinical stage in patients." (PMID 36376369, 2022). "With regard to the clinicopathological characteristics, our analysis demonstrated that elevated expression level of PANDAR was associated significantly with advanced tumor stage, deeper depth of invasion, more lymph node metastasis and farther distant metastasis." (PMID 31850222, 2019). "The expression of PANDAR was significantly correlated with the history of digestive system (P = 0.035), TNM stage (P = 0.047) and lymph node metastasis (P = 0.023) of patients." (PMID 40713854, 2025). "This study showed that the overexpression of PANDAR is connected with clinical features of patients with GC, including the history of digestive system, TNM stage and lymph node metastasis." (PMID 40713854, 2025). "Moreover, PANDAR expression level was related to clinicopathological characteristics including TNM stage, depth of invasion, lymph node metastasis, and distant metastasis." (PMID 31850222, 2019). "In addition, we demonstrated that increased PANDAR expression was positively correlated with an advanced TNM stage, lymph node metastases, distant metastases and poor prognosis." (PMID 28545465, 2017). "In addition, multivariate analysis indicated that the expression of PANDAR was an independent prognostic factor for the overall survival of patients in line with the TNM stage, the Fuhrman grade, lymph node metastases and distant metastases." (PMID 28545465, 2017).
colon cancer (1 paper, 2021). "Additionally, high PANDAR levels in colon cancer predict poor patient prognosis and promote metastasis through EMT." (PMID 37551364, 2021). "Indeed, it was previously reported that high expression of PANDAR in colon cancer predicts poor patient prognosis and promotes metastasis through EMT." (PMID 37551364, 2021).
glioma (1 paper, 2021). A benign or malignant brain and spinal cord tumor that arises from glial cells (astrocytes, oligodendrocytes, ependymal cells). "While the role of PANDAR has been evaluated in many cancers its association with glioma has not been studied." (PMID 33926464, 2021).
renal carcinoma (1 paper, 2017). A carcinoma arising from the epithelium of the renal parenchyma or the renal pelvis. "The relative expression level of lncRNA PANDAR was quantified by real-time qPCR in 62 paired ccRCC tissues and in renal cancer cell lines, and its association with overall survival was assessed by statistical analysis." (PMID 28545465, 2017).
renal cell carcinoma (1 paper, 2019). "However, no significant relation was found between PANDAR expression level with OS of patients suffering from renal cell carcinoma." (PMID 31850222, 2019).
thyroid tumours (1 paper, 2021). "The luciferase reporter assay also showed that lincRNA PANDAR can target miR-637, and PANDAR can affect the proliferation and metastasis of thyroid tumours by regulating miR-637." (PMID 34476001, 2021).
cancer (30 papers, 2013 to 2025). A tumor composed of atypical neoplastic, often pleomorphic cells that invade other tissues. "Our results indicated that the high expression level of PANDAR was associated with poor OS significantly in cancer patients." (PMID 31850222, 2019). "Our results imply that PANDAR is not only a powerful diagnostic biomarker for GC patients but also a promising potential therapeutic target for cancer treatment." (PMID 29416011, 2018). "The overexpression of PANDAR in cancer patients was closely associated with a higher histological grade, advanced TNM stage and poorer overall survival." (PMID 29416011, 2018). "Of particular interest is the association with the PANDAR ncRNA, which is thought to regulate the response to DNA damage, and whose deregulation induced cancer progression." (PMID 30485296, 2018). "This gene is also a target associated to the PANDAR ncRNA, therapeutically relevant because of its aberrant expression observed in various cancers." (PMID 30485296, 2018). "In summary, lncRNA PANDAR is overexpressed in GC, and promotes the development of GC as a cancer-promoting factor." (PMID 40713854, 2025). "We knocked down PANDAR expression in TPC-1 and K1 cancer cells by transfection with NC-siRNAs or si-PANDAR." (PMID 34476001, 2021). "Mounting evidence has illustrated the oncogenic function of PANDAR in other carcinomas except for OSCC." (PMID 33842552, 2021). "LncRNA PANDAR acts as a cancer suppressor gene by regulating Bcl-2 to affect cell apoptosis in NSCLC." (PMID 31558162, 2019). "Recently, PANDAR was known as biomarkers of cancer and potentially involved in the instability of chromosomes and cancer metastatic progression." (PMID 31850222, 2019). "In order to explore the more important role of PANDAR in human cancer, more relevant researches will be needed in the future." (PMID 31850222, 2019). "Odds ratios (ORs) or hazards ratios (HRs) with 95% confidence intervals (CIs) were pooled to estimate the relation between PANDAR expression and survival or clinicopathological characteristics of cancer patients." (PMID 31850222, 2019). "Several lncRNAs have been confirmed to play an important role in various types of malignant tumors, including PANDAR, ZFAS1, HOTAIR, TUG1 and so on23–26." (PMID 30111807, 2018). "Through this unique transcriptional modification pattern, PANDAR notably facilitated cancer cell proliferation, clone formation and chemotherapy resistance." (PMID 29416011, 2018). "Recently, several lncRNAs have been found to play an emerging role in various cancers, contributing to tumor proliferation, apoptosis, and survival, such as PANDAR, MEG3." (PMID 27514530, 2016). "Although PANDAR has been studied during DNA damage in human fibroblasts, a variety of physiological and pathological processes and the possible role of PANDAR in cancer including NSCLC remains to be clarified." (PMID 25719249, 2015). "Therefore, PANDAR acts as a cancer-promoting factor in GC cells, driving tumorigenesis and metastatic progression." (PMID 40713854, 2025). "Knockdown of PANDAR expression inhibited cancer progression in nude mice." (PMID 34476001, 2021). "Moreover, we found that PANDAR was an independent prognostic factor of OS in cancer patients when combined with HRs from Cox multivariate analysis." (PMID 31850222, 2019).
cancer (continued). "Despite the fact that recent studies have revealed that lncRNA PANDAR may be a potential prognostic biomarker for patients with cancer, there has still been controversy on the prognostic value of PANDAR." (PMID 31850222, 2019). "Our results showed that the association between the reduced expression level of PANDAR with poor EFS in cancer patients was not significant." (PMID 31850222, 2019). "Hence, we conducted a current and comprehensive meta-analysis to elucidate the prognosis and clinicopathological significance of PANDAR expression in patients diagnosed as cancer." (PMID 31850222, 2019). "In addition, we performed Cox multivariate analysis in nine studies including nine cohorts, finding that elevated expression level of PANDAR was an independent prognostic factor for OS in these cancer patients (HR 1.94, 95% CI 1.25–3.02, p = 0.003)." (PMID 31850222, 2019). "Furthermore, the overexpression of PANDAR promoted S phase entry and suppressed the cancer cell apoptotic activity." (PMID 29416011, 2018). "Due to the fact that the function of PANDAR in different cancers is still controversial and remains to be clarified, we conducted this meta-analysis to investigate the clinicopathological significance and prognostic value of abnormal PANDAR expression in patients suffering from cancer." (PMID 31850222, 2019). "Therefore, we could conclude that the expression level of PANDAR might play different roles in predicting OS in several kinds of cancers." (PMID 31850222, 2019). "Since PANDAR is known to be upregulated in several cancer types, it would be of utmost importance to investigate, if the identified RNA-protein interactions contribute to the pathological phenotype and might even open up the possibility for new therapeutic targets." (PMID 29434205, 2018). "To clarify the roles of PANDAR in NSCLC development, we explored the PANDAR expression status in tissues and found the expression of PANDAR in cancer tissues was downregulated compared to normal tissues (P < 0.05)." (PMID 32626525, 2020). "Located upstream of the CDKN1A promoter, PANDAR (Promoter of CDKN1A Antisense DNA Damage Activated RNA) is involved in cell proliferation, migration, invasion, and apoptosis of cancer cells and are widely overexpressed in solid tumors." (PMID 31653018, 2019). "However, the involvement of PANDAR in cancer chemoresistance is unknown." (PMID 30375398, 2018). "Therefore, PANDAR may play an important role in the development of cancers." (PMID 28545465, 2017). "We knocked down PANDAR expression in TPC-1 and SW579 cancer cells by transfection with NC-siRNAs, si-PANDAR." (PMID 28507479, 2017). "Four cancer cell lines (A549, SPC-A1, SK-MES-1 and NCI-H1299) expressed lower levels of PANDAR compared with the normal bronchial epithelial cell line (16HBE)." (PMID 25719249, 2015). "PANDAR interacts with polycomb repressive complexes (PRC1 and PRC2) and the transcription factor NF-YA to repress the transcription of senescence-promoting genes in cancer cells." (PMID 27206339, 2016).